AGAP4 (ArfGAP with GTPase domain, ankyrin repeat and PH domain 4)
Description:
Putative GTPase-activating protein.
Synonyms: AGAP-4; AGAP8; CTGLF1; CTGLF5; MRIP2; Em:AC012044.1; AGAP-8
Tractability: No criterion of Open Targets' tractability assessment is met for any kind of drug.
Gene: Protein-coding gene on chromosome 10 (45,825,594 to 45,853,875, reverse strand). Ensembl gene ENSG00000188234.
Gene Ontology:
Molecular function: GTPase activator activity; GTPase activity
Genetic constraint (gnomAD): Loss-of-function variants: 9 observed, 20.64 expected, observed/expected ratio (o/e) 0.44, 90% interval 0.26 to 0.76. The synonymous counts are far from expectation, so gnomAD's model fits this gene poorly and the ratio says little. Missense variants: 139 observed, 347.18 expected, observed/expected ratio (o/e) 0.4, 90% interval 0.35 to 0.46. Synonymous variants: 57 observed, 130.24 expected, observed/expected ratio (o/e) 0.44, 90% interval 0.35 to 0.55.
Homologues: Paralogues in human: AGAP6 (98% identical), AGAP5 (97% identical), AGAP9 (91% identical), AGAP1 (62% identical), AGAP3 (48% identical), AGAP2 (43% identical), ACAP3 (19% identical), ACAP2 (18% identical), ASAP2 (17% identical), ASAP1 (17% identical), ACAP1 (17% identical), ASAP3 (16% identical), and 16 more.
Diseases named in the same sentence as AGAP4 in open-access papers:
AGAP4 is named in the same sentence as 8 diseases in open-access papers, as found by Europe PMC text mining. Sharing a sentence is not in itself a finding about the gene and the disease. The quoted sentences say what the papers report.
basal cell carcinoma (1 paper, 2022). A carcinoma involving the basal cells. "AGAP4/6 expression alterations were proved that would result to multiple cutaneous basal cell carcinomas." (PMID 36072430, 2022).
cancer (3 papers, 2022 to 2025). A tumor composed of atypical neoplastic, often pleomorphic cells that invade other tissues. "AGAP4 and AGAP6 have not been previously reported; they belong to the GTPase-activating protein family that play a vital role in cancer progression." (PMID 36100894, 2022).
AGAP4 also shares sentences with these, for which no sentence is quoted: breast carcinoma (1 paper); glioma (1); infection (1); neurodevelopmental disorder (1); prostate carcinoma (1); tumour (1).